FMN1 (formin 1)
Description:
Plays a role in the formation of adherens junction and the polymerization of linear actin cables.
Synonyms: FMN; LD; DKFZP686C2281; FLJ45135; MGC125288; MGC125289
Tractability: Antibody: UniProt places it where antibodies can reach, with medium confidence; its Gene Ontology location is reachable by antibodies, with medium confidence. PROTAC: ubiquitination databases record sites on it.
Gene: Protein-coding gene on chromosome 15 (32,765,544 to 33,194,714, reverse strand). Ensembl gene ENSG00000248905.
Subcellular location: Nucleus; Cytoplasm; Cell junction, adherens junction; Cell membrane
Subcellular location (Human Protein Atlas): Nucleoplasm; Cytosol
Gene Ontology:
Molecular function: actin binding; microtubule binding; SH3 domain binding
Biological process: formin-nucleated actin cable assembly; actin nucleation
Cellular component: cytosol; nucleoplasm; endoplasmic reticulum membrane; microtubule cytoskeleton; nucleus; actin filament; adherens junction; cytoplasm; plasma membrane
Genetic constraint (gnomAD): Loss-of-function variants: 77 observed, 92.85 expected, observed/expected ratio (o/e) 0.83, 90% interval 0.69 to 1. The upper end of that interval is the gene's LOEUF score, 1, which puts it in group 4 of 6, group 1 being the genes least tolerant of losing a copy. Missense variants: 1,501 observed, 1,478.5 expected, observed/expected ratio (o/e) 1.02, 90% interval 0.97 to 1.06. Synonymous variants: 587 observed, 571.87 expected, observed/expected ratio (o/e) 1.03, 90% interval 0.96 to 1.1.
Homologues: Orthologues: chimpanzee FMN1 (99% identical), macaque FMN1 (95% identical), pig FMN1 (81% identical), rabbit FMN1 (80% identical), dog FMN1 (80% identical), rat Fmn1 (78% identical), guinea pig FMN1 (72% identical), mouse Fmn1 (71% identical), tropical clawed frog fmn1 (44% identical), zebrafish fmn1 (29% identical), zebrafish si:rp71-62i8.1 (8% identical), zebrafish si:ch1073-209e23.1 (5% identical).
Diseases named in the same sentence as FMN1 in open-access papers:
FMN1 is named in the same sentence as 35 diseases in open-access papers, as found by Europe PMC text mining. Sharing a sentence is not in itself a finding about the gene and the disease. The quoted sentences say what the papers report.
colorectal cancer (3 papers, 2020 to 2025). A primary or metastatic malignant neoplasm that affects the colon or rectum. "FMN1 variants have been linked to the occurrence of colorectal cancer, glioma, and pancreatic cancer." (PMID 40740763, 2025). "This gene-environment interaction analysis revealed a genetic locus in FMN1/GREM1 that interacts with body mass index in colorectal cancer risk, suggesting potential implications for precision prevention strategies." (PMID 37249599, 2023). "Our novel G×BMI finding at the FMN1/GREM1 locus is close to a region with multiple known GWAS loci for colorectal cancer risk." (PMID 37249599, 2023). "Using data from three large international consortia, this study discovered a locus in the FMN1/GREM1 gene region that interacts with BMI on the association with colorectal cancer risk." (PMID 37249599, 2023). "In conclusion, we identified a new locus in the FMN1/GREM1 gene region that interacts with BMI on the association with colorectal cancer risk." (PMID 37249599, 2023). "It is possible that FMN1 acts in tandem with neighboring genes, such as GREM1 and SCG5 because the catena SCG5-GREM1-FMN1 constitutes a hotspot for several colorectal cancer–related SNPs." (PMID 37249599, 2023). "In this study from three large international colorectal cancer consortia, we discovered a new locus located within the FMN1/GREM1 gene region (rs58349661) that interacts with BMI on the association with colorectal cancer risk." (PMID 37249599, 2023). "In the two-step EDGE approach, we observed a statistically significant interaction between variants located in the formin 1/Gremlin 1 (FMN1/GREM1) gene region and BMI in colorectal cancer risk." (PMID 37249599, 2023). "A variety of Formins but not FMN1, have been implicated in invasion and metastasis of colorectal cancer." (PMID 37249599, 2023). "Although very little is known about FMN1 and colorectal cancer, there are extensive data on formins, more generally, their role in developmental biology, WNT signaling, and their association with colorectal cancer." (PMID 37249599, 2023).
Obesity (2 papers, 2020 to 2023). Accumulation of substantial excess body fat. "Additional studies are necessary to fully understand the possible contribution of FMN1 to colorectal tumor development according to obesity status." (PMID 37249599, 2023). "In contrast to the tumor-promoting profile of SMAD7 in obesity, FMN1 does not have a clear relationship with inflammation." (PMID 37249599, 2023). "Still, whether through the regulation of BMSCs differentiation (FMN1 and BMPR1B), glucose metabolism (MAGI2), or initiation of the inflammatory process (SKAP2), these genes could be relevant to the development of obesity." (PMID 33003475, 2020).
autism (1 paper, 2022). Persistent deficits in social interaction and communication and interaction as well as a markedly restricted repertoire of activity and interest as well as repetitive patterns of behavior. "We hypothesize that genes severely dysregulated in autism such as SCN1B, KCNAB3, FMN1, or VAMP1 might additionally contribute to the excitation-to-inhibition ratio affecting normal network function and circuitry." (PMID 35680911, 2022).
autoimmune disease (1 paper, 2022). A disorder resulting from loss of function or tissue destruction of an organ or multiple organs, arising from humoral or cellular immune responses of the individual to their own tissue constituents. "Up-regulation of FMN1 in T cells has been observed in the context of autoimmunity, while impaired expression of FMN1 has been found to hinder the induction of autoimmune diseases." (PMID 36077551, 2022).
cardiac hypertrophy (1 paper, 2015). "We propose that the overexpression of FMN1 found in our study may lead to the activation of RhoA/ROCK signaling pathways implicating further development of cardiac hypertrophy." (PMID 25984239, 2015).
chronic pancreatitis (1 paper, 2020). A chronic inflammatory process causing damage and fibrosis of the pancreatic parenchyma. "More importantly, FMN1 has also been identified as a candidate gene for susceptibility to chronic pancreatitis 54 predisposing the hosts to 13.3‐fold increased risk of PanC." (PMID 33200553, 2020).
COVID-19 (1 paper, 2022). A disease caused by infection with severe acute respiratory syndrome coronavirus 2. "Our study revealed that serum levels of FMN1 [Q68DA7] were significantly elevated in the post-COVID-19 group compared to the uninfected." (PMID 36077551, 2022). "The coding gene of FMN1 was found to be highly expressed in lung cell types of COVID-19 patients compared to healthy controls." (PMID 36077551, 2022).
diabetes (1 paper, 2010). "However, there is very limited evidence about genetic variation on CAMK4 or FMN1 and diabetes or its complications." (PMID 20871662, 2010).
diabetic nephropathy (1 paper, 2010). "Based on the fact that both Gremlin and FMN1 have important implications for renal system, and the role of FMN1 in gremlin transcriptional regulation, it would be very interesting to investigate whether FMN1 are also associated with diabetic nephropathy in the future study." (PMID 20661431, 2010).
melanoma (1 paper, 2021). A malignant, usually aggressive tumor composed of atypical, neoplastic melanocytes. "Formin 1 (FMN1) is involved in the formation of adherens junctions and actin organization, and other formin family genes (FMNL2/FMNL3) have been shown to play a role in melanoma biology." (PMID 34281234, 2021).
mental disorder (1 paper, 2021). A disease that has its basis in the disruption of mental process. "The possible involvement of FMN1 mutations in these mental disorders could be explained by the role of FMN1 in the glutamatergic synaptic terminals." (PMID 34685534, 2021).
obsessive-compulsive disorder (1 paper, 2017). A disorder characterized by the presence of persistent and recurrent irrational thoughts (obsessions), resulting in marked anxiety and repetitive excessive behaviors (compulsions) as a way to try to decrease that anxiety. "A microdeletion encompassing part of the FMN1 gene has been recently reported in a patient with early-onset obsessive-compulsive disorder; interestingly, this deletion includes the FMN1 exon (exon 5) containing the described mutation." (PMID 28787007, 2017).
Sepsis (1 paper, 2024). Sepsis is defined as life-threatening organ dysfunction caused by a dysregulated host response to infection. "While FMN1’s role in inflammation and sepsis has not been extensively studied, it has been implicated in cell migration and immune cell function, suggesting a potential involvement in inflammatory processes." (PMID 38167131, 2024).
tuberculosis (1 paper, 2022). A chronic, recurrent infection caused by the bacterium Mycobacterium tuberculosis. "FMN1 expression is often dysregulated in the immune system such as in CD8 T-cells from pediatric patients with influenza-like illness or monocytes from patients with tuberculosis-associated immune reconstitution inflammatory syndrome, indicating its role in the immunological pathway." (PMID 35432474, 2022).
cancer (6 papers, 2014 to 2025). A tumor composed of atypical neoplastic, often pleomorphic cells that invade other tissues. "It has been reported that FMN1 expression is associated with motility in different cancer cell lines, and its ectopic expression has been shown to boost fitness indices." (PMID 36498797, 2022). "All three genes (i.e., TRAT1, POGZ, and FMN1) have been identified as potential therapeutic targets for the treatment of some cancers." (PMID 38396979, 2024). "We additionally identified recurrent mutations in RYR2, FMN1, B3GNT9 and PIEZO2 in our discovery set of cancers, but the importance of these genes for bladder carcinogenesis remains uncertain." (PMID 24777035, 2014). "Further studies are necessary to establish whether FNBP4 physiologically regulates FMN1 in the nucleus and promotes cancer progression by modulating nuclear actin dynamics." (PMID 40316024, 2025).
tumor (4 papers, 2015 to 2023). "The expression of MEIS2, FMN1 and CTDSPL2 proteins is associated with impaired renal function and can be regulated by tRF-5b, which can replace miR-458 during tumor suppression." (PMID 35409004, 2022). "However, poor patient status, associated with an immunological condition and GBM microenvironment, may have affected the invasive tumor phenotype, including FMN1 expression." (PMID 31861134, 2019).
kidney disorder (1 paper, 2019). A disease involving the kidney. "Both PAH and FMN1 were reported to be related to kidney disorders, which implies a potentially target pathway for the study of renal complications in patients with T2D." (PMID 31888606, 2019).
FMN1 also shares sentences with these, for which no sentence is quoted: diabetic retinopathy (2 papers); pancreatic cancer (2); alcoholic cirrhosis (1); atherosclerosis (1); Autoimmunity (1); Cirrhosis (1); colorectal tumor (1); glioma (1); heart failure (1); infection (1); infectious disease (1); myocardial infarction (1); neuropathic pain (1); ovarian carcinoma (1); prostate carcinoma (1); pulmonary fibrosis (1); type 2 diabetes (1); viral hepatitis (1).